ZXDB (zinc finger X-linked duplicated B)
Description:
Cooperates with CIITA to promote transcription of MHC class I and MHC class II genes.
Synonyms: ZNF905; dJ83L6.1
Tractability: PROTAC: ubiquitination databases record sites on it.
Gene: Protein-coding gene on chromosome X (57,592,011 to 57,597,477, forward strand). Ensembl gene ENSG00000198455.
Subcellular location: Nucleus
Subcellular location (Human Protein Atlas): Nucleoplasm
Gene Ontology:
Molecular function: protein binding; transcription coregulator activity; C2H2 zinc finger domain binding; transcription coactivator activity
Biological process: regulation of transcription by RNA polymerase II; positive regulation of DNA-templated transcription
Cellular component: nucleus
Homologues: Orthologues: chimpanzee ZXDB (97% identical), tropical clawed frog zxdc (47% identical), zebrafish si:dkey-156n14.3 (41% identical), Drosophila melanogaster ci (13% identical), Drosophila melanogaster lmd (12% identical), zebrafish zic6 (11% identical), Drosophila melanogaster opa (11% identical), Caenorhabditis elegans tra-1 (11% identical), Caenorhabditis elegans ref-2 (8% identical), Caenorhabditis elegans ztf-14 (8% identical). Paralogues in human: ZXDA (96% identical), ZXDC (57% identical), GLI2 (17% identical), GLI3 (17% identical), GLIS3 (15% identical), GLI1 (14% identical), GLIS1 (14% identical), ZIC3 (13% identical), ZIC2 (13% identical), ZIC1 (13% identical), ZIC5 (13% identical), GLIS2 (13% identical), and 2 more.
Diseases named in the same sentence as ZXDB in open-access papers:
ZXDB is named in the same sentence as 1 disease in open-access papers, as found by Europe PMC text mining. Sharing a sentence is not in itself a finding about the gene and the disease. The quoted sentences say what the papers report.
cancer (1 paper, 2017). A tumor composed of atypical neoplastic, often pleomorphic cells that invade other tissues. "Those CNC variations associated with poor outcome (MUC5B, ZXDB, PLIN4, CCDC144NL, CNTNAP3B, and CCDC180) may probably facilitate cancer initiation and progression, and may be a new clue to study cancer metastasis and evolution." (PMID 29262625, 2017).